ICAM1 (intercellular adhesion molecule 1)
Diseases named in the same sentence as ICAM1 in open-access papers (continued):
Sharing a sentence is not in itself a finding about the gene and the disease.
tumor (continued). "It was recently reported that the protein intercellular cell adhesion molecule-1 (ICAM-1) is an important factor for the maintenance of malignant potential of cancer and that the protein stability of is associated with tumor progression." (PMID 29137327, 2017). "The IL-35 expression level in PDAC tissues was significantly associated with the ICAM1 expression level (r=0.274, P=0.0020, Spearman's correlation analysis), that is, tumour tissues with a high IL-35 level usually had a high ICAM1 expression." (PMID 28102193, 2017). "Because ICAM1 is essential for activating cytotoxic T-lymphocytes (CTLs), miR-222 and miR-339 in tumor cells downregulate the susceptibility of tumor cells to CTL-mediated cytolysis." (PMID 28486396, 2017). "In our study, the continued expansion of the nanomolar affinity F292G CAR T cells despite tumor elimination was likely caused by activation of CAR T cells by inflammation-induced murine ICAM-1." (PMID 29085043, 2017). "Several studies have shown a critical role of MMP9 in tumor angiogenesis and have linked ICAM1 to intra-tumor microvessel density." (PMID 28977919, 2017). "Here, a panel of affinity-variant CARs were constructed targeting overexpressed ICAM-1, a broad tumor biomarker, using its physiological ligand, LFA-1." (PMID 29085043, 2017). "Compared with normal kidney, the ECM components and mechanics-associated genes (from PLOD2 to ICAM1) in tumor tissues were significantly increased in ccRCC patients." (PMID 28846080, 2017). "They found that ICAM-1 rs5498 G allele is associated with increased tumor grade (OR = 2.650) and risk (OR = 1.405)." (PMID 27252704, 2016). "22, 56 We show herein that blockade of ICAM-1 deficiency-mediated efferocytosis with a pharmacologic inhibitor can attenuate macrophages toward M2 polarization in the tumor microenvironment." (PMID 26068788, 2015). "To explore the physiologic consequences of loss of ICAM-1 in macrophages, we performed a series of efferocytosis assays to investigate the impact of this protein on the phagocytic capacity of apoptotic tumor cells." (PMID 26068788, 2015). "We further demonstrated that ICAM-1 deficiency in macrophages led to promotion of efferocytosis of apoptotic tumor cells through activation of the phosphatidylinositol 3 kinase/Akt signaling pathway." (PMID 26068788, 2015). "Additional serum markers currently being explored include tumor-associated isoenzymes of gamma-glutamyl transpeptidase, urinary transforming growth factor-beta 1, and serum levels of circulating intercellular adhesion molecule-1." (PMID 29201680, 2015). "The cellular adhesion molecule, ICAM-1 has also been implicated in various stages of tumor progression and metastasis, whereas COX-2 contributes to different stages of cancer development including uncontrolled growth, metastasis and angiogenesis." (PMID 25762616, 2015). "In this study, the interactions between macrophages and tumor cells were investigated, with focus on efferocytosis and its effects on macrophage polarization via ICAM-1 deficiency." (PMID 26068788, 2015). "More recently, a study further demonstrated that tumor-associated fibroblasts isolated from tumor tissues exhibit increased ICAM-1 expression and affinity for monocytes." (PMID 24667577, 2014). "ICAM-1 has been associated with cellular migration into inflammatory sites and with facilitating interactions between lymphocytes and tumor targets in the pathway of cell-mediated cytotoxicity." (PMID 24742333, 2014). "ICAM-1 is constitutively expressed at low levels on the surface of various cell types; it is cytokine-inducible and has been implicated in tumor prognosis, progression, and metastasis of cancer." (PMID 23024755, 2012). "Several adhesion molecules, including ICAM-1, have been implicated in the tumor transformation and metastasis via the mediating adhesion of cancer cells to the vascular endothelium." (PMID 23098564, 2012).
tumor (continued). "Elevated expression of ICAM-1 has been associated with tumor progression in certain types of cancers." (PMID 23300837, 2012). "Our study demonstrated an association between CD3ε, CD25, CD68, and ICAM-1 mRNA levels in BCC tumor biopsies and the risk for subsequent tumors." (PMID 21980389, 2011). "Low ICAM-1 mRNA levels in tumor biopsies had a borderline association with shorter tumor-free periods (p = 0.08)." (PMID 21980389, 2011). "We have reported that sFn cross-linked platelet binding to tumor cells via the major platelet fibrin receptor αIIbβ3, and tumor cell CD54 (ICAM-1), which is the receptor for two of the leukocyte β2 integrins (αLβ2 and aMβ2)." (PMID 16925817, 2006). "Intercellular adhesion molecule (ICAM-1) exists as a membrane-associated form (mICAM-1) on the surface of tumour cells as well as a soluble form (sICAM-1)." (PMID 10408388, 1999). "Addition of blocking ICAM-1 antibody (10 μg ml−1) to the C8161 cells at an effector:tumour cell ratio of 40:1 caused a 2.3-fold reduction in lysis of tumour cells and a 3-fold reduction in lysis of RA-treated cells." (PMID 10408388, 1999). "In conclusion, serum levels of sICAM-1 seem to be associated with tumour burden and histological expression of ICAM-1 in patients with NSCLC." (PMID 9514061, 1998). "Interestingly, certain epigenetic therapies, such as decitabine, have been shown to upregulate ICAM-1 expression on tumor cells, enhancing their susceptibility to immune cell-mediated lysis." (PMID 40597436, 2025). "Additionally, they reduce recruitment of M2-type tumor-associated macrophages (TAMs) and regulatory T cells (Tregs), promote M1 polarization, and modulate immune-related genes such as ICAM-1, enhancing pro-inflammatory signaling including IFN-γ." (PMID 41550934, 2025). "Additionally, a reduction in CXCR2 and intercellular adhesion molecule 1 (ICAM-1) was associated with decreased tumor neutrophil infiltration." (PMID 41011849, 2025). "CD49b was expressed in 71.11% (32/45) of normal tissues, CD73 in 86.05% (37/43), and EGFR in 46.67% (21/45), which may cause more on-target-off-tumor toxicities in contrast to ICAM1 in 19.15% (9/47)." (PMID 39971940, 2025). "For example, PGE2 binding with EP1 activates protein kinase C (PKC)/nuclear factor-κB (NF-κB)/human forkhead box protein C2 (FOXC2) and EGFR/PI3K signaling pathways, which increases intercellular adhesion molecule-1 (ICAM-1), thereby causing tumor growth and migration." (PMID 38704736, 2024). "However, reintroducing ICAM1 into LKB1-deficient tumors reactivates interactions between tumor cells and effector cells, leading to enhanced homing and activation of CD8+ T cells and resensitization of the tumor to ICB." (PMID 39802954, 2024). "Soluble intercellular adhesion molecule-1 (ICAM-1) has recently been found in urine following BCG treatment, and ICAM-1 expression on tumor cells may predispose tumor cells to cell-mediated cytotoxicity." (PMID 38659423, 2024). "Notably, disrupting the ICAM-1–FGG interaction using ICAM-1Δ8-22 mutation showed similar tumor inhibition as knockdown of ICAM-1 or FGG." (PMID 39168965, 2024). "Icam-1, a cell membrane surface glycoprotein weighing 90 kDa, was initially found to interact with leukocyte function-associated antigen-1, facilitating the adhesion of white blood cells or tumor cells to endothelial cells." (PMID 38463490, 2024). "Moreover, ICAM-1 was expected to be associated with perivascular regions, but majority of the panobinostat-induced expression was within the tumor and neutrophil compartments." (PMID 36672243, 2023). "Taken together, these data suggest that ICAM1 may be prerequisite for the homing of activated tumor-specific T cells in LKB1-deficient tumors." (PMID 36871040, 2023). "Finally, we co-cultured tumor cells transfected with ICAM-1 variants with PBMCs containing expanded antigen specific CTLs and monitored tumor cell killing over time." (PMID 37732732, 2023).
tumor (continued). "Moreover, Zhang and his colleagues found that ICAM1-lymphocyte-function-associated antigen-1-mediated adhesion between tumor-derived extracellular vesicles, and T cells was a prerequisite for exosomal PD-L1-mediated immune suppression." (PMID 38111045, 2023). "MSI1 causes tumor migration by binding with ICAM1 RNA, leading to poor prognosis." (PMID 35887658, 2022). "The roles of different mediators, which include Toll-like receptors, lymphotoxin beta (LTB), intercellular adhesion molecule 1 (ICAM1), interferon beta, chemokines, and cytokines, are linked to the NF-κB activation and promotion of tumor regression, leading to better disease prognosis." (PMID 36518665, 2022). "First, these nanoparticles can be actively accumulated in the tumor microenvironment due to the presence of inherited lymphocyte function-associated antigen 1 on the nanoparticles and intercellular adhesion molecule-1 on the affected endothelial cells in the tumor tissue." (PMID 34440380, 2021). "In this study, we show that tumor-associated neutrophils expressed ICAM-1 and IL-1β in the lungs." (PMID 34257370, 2021). "Moreover, Dicer-generated miR-222 and miR-339 suppress ICAM-1 on tumor cells, leading to the decreased susceptibility to cytotoxic T-cells cytolysis." (PMID 33321819, 2020). "In addition, the loss of adhesion molecules, e.g., ICAM-1, and the frequency of tumor infiltrating lymphocytes (TILs) interferes with anti-tumor responses." (PMID 32987799, 2020). "Thus, overexpression of ICAM-1, observed on many malignantly transformed cells, can serve as a predictor of tumor cell susceptibility to CVA21-mediated oncolysis." (PMID 31262361, 2019). "Also systemic thermal therapy (STT) induced the activation of IL-6 trans-signaling causing up-regulation of ICAM-1 on tumor vascular endothelium and thus increased the homing of adoptively transferred CD8+ T cells into tumors in mouse models of cancer." (PMID 31231358, 2019). "In previous studies, we could demonstrate a significantly higher expression of ICAM-1 in tumor-associated fibroblasts as compared to normal tissue-associated fibroblasts." (PMID 30470940, 2019). "Interestingly, lower levels of EWS-FLI1 are associated with increased expression of ICAM-1, a surface protein reported in some cancers to influence tumor cell: T-cell interaction and promote T-cell activation." (PMID 30400822, 2018). "Similarly, there also exists a separate pathway in which IL-1α upregulates the release of sICAM from tumour-associated endothelial cells even in tumours expressing low levels of membrane-bound ICAM-1." (PMID 29772648, 2018). "It is intriguing to speculate that it might be the cytokine production within the tumor microenvironment that causes the expression of ICAM1 in the tumor cells, since TNFα and IFNγ are known to induce synthesis of ICAM147." (PMID 30082828, 2018). "IHC results showed that fractalkine and ICAM-1 expressions were associated with higher tumor stage." (PMID 28903329, 2017). "These NCR+ ILC3s interacted with tumor cells and tumor-associated fibroblasts via their NKp44 receptor to trigger production of LTαβ, which resulted in the activation of endothelial cells and mesenchymal stem cells, including upregulation of ICAM-1 and VCAM-1." (PMID 27752256, 2016). "Intercellular adhesion molecule (ICAM)-1, a cell adhesion molecule with a key role in inflammation and immunosurveillance, was implicated in carcinogenesis by facilitating instability in the tumor environment." (PMID 24069166, 2013). "Similarly, miR-222 and miR-339, though primarily associated with T cells, downregulate ICAM-1 and may impair NK cell–tumor interactions." (PMID 40647470, 2025). "In addition, tumor-associated HEVs exhibit elevated ICAM-1 expression, which may further facilitate lymphocyte infiltration into tumors and support the formation of tertiary lymphoid structures." (PMID 39911389, 2025).
tumor (continued). "Other reports, however, disputed these findings, suggesting that paclitaxel might improve the removal of tumor cells through NK cells by boosting their cytotoxic effects, prompting the expression of ICAM-1 and MIC-B, and/or by making melanoma cells more susceptible to death." (PMID 38057843, 2023). "ICAM-1 may also suppress M2 polarisation of tumour-associated macrophages." (PMID 36586434, 2023). "It would be interesting to investigate in future whether CD103 expression on CTLs is associated with E-cadherin or ICAM-1 expression on tumour cells and strong adhesion between the molecules expressed by tumour cells and CD103 on CTLs is required for efficient tumour reduction." (PMID 36626205, 2023). "Similarly, ICAM1 (Intercellular adhesion molecule) is also associated with cancer progression and invasion, and was overexpressed in the outliers (6.64x higher than in control samples (q = 0,00025) and 3.12x higher in tumor samples)." (PMID 30419021, 2018). "Yet, the mechanisms by which CAF-associated ICAM-1 acts as a tumor promoter remain unclear." (PMID 27901489, 2017). "Moreover, ICAM-1 deficiency increased M2 macrophage polarization during tumor progression." (PMID 26068788, 2015). "In addition, the ICAM-1 expression has been associated with a more aggressive tumour phenotype." (PMID 24857933, 2014). "ICAM-1 shedding by tumor cells into the microenvironment might be associated with T/NK-cell mediated death resistance, since soluble ICAM-1 would act as a decoy ligand, binding surface receptors of NK-cells and preventing them from recognizing molecules displayed on the surface of the tumor cells." (PMID 24086377, 2013). "Similarly for epithelial-type CTCs, tumor associated MUC1 may play the role of beta-2 integrins on leukocytes by binding ICAM-1 to enable firm adhesion and initiate subsequent events in the metastatic cascade." (PMID 22866263, 2012). "These cytokines are considered to prepare the ground for cellular assault by causing tumor cells to display molecules that serve as attachment anchors for immune cells, including neutrophils and T lymphocytes, and activation signals such as ICAM-1, fatty-acid synthetase (FAS), CD40, etc." (PMID 24212945, 2011). "CD18 on neutrophils facilitates tumor cell extravasation through binding with ICAM1 on tumor cells, which was also shown with the higher expression with RT than without RT in these models." (PMID 41486114, 2026). "This increase facilitates the escort of tumor cells into bloodstream through directly binding ICAM1 on their surface, and ultimately leads to LM in both the inherently neutrophil-enriched MB49 and LLC mouse models." (PMID 41486114, 2026). "Although ICAM-1 exerts tumor-suppressive effects, its involvement in ferroptosis-driven TNBC growth arrest remains elusive." (PMID 41518487, 2026). "The expression of inflammatory and tumor-associated genes (IL-8, MCP-1, TIMP-2, ICAM-1 and NF-kB) was assessed by quantitative PCR." (PMID 42072644, 2026). "In vitro, WT, but not Cxcr2-/-, neutrophils enhanced CD8+ T cell activation, partly via ICAM-1, and directly induced tumor cell death, supporting their anti-tumor function." (PMID 41977328, 2026). "Higher ICAM1 and lower RAET1E expression were associated with advanced tumor stage and unfavorable survival outcomes." (PMID 42317355, 2026). "CD18, as an integrin β2 subunit, is know to facilitate neutrophil adhesion to endothelial cells via ICAM-1, thereby promoting their migration into tumor sites and potentially enhancing their immunosuppressive activity." (PMID 40549016, 2025). "A defect in either ICAM-1 or VCAM-1 will result in decreased adhesion of the T-cell to the tumor epithelium, blunting the immunogenic response and resulting in resistance to therapy options." (PMID 40872475, 2025).
tumor (continued). "A separate investigation on a similar MPS revealed that fibrinogen forms bridges between intercellular adhesion molecule-1 (ICAM-1) receptors on both endothelial and tumor cells, thereby increasing tumor cell adhesion and extravasation." (PMID 41123820, 2025). "Loss of pancreatic secretion-related genes along with alterations in ICAM1 and CEACAM5, contribute to the loss of normal exocrine function and promote tumor microenvironment remodeling." (PMID 40226632, 2025). "Cytokine treatment significantly increased the expression of FAS, TRAIL-R2, and ICAM-1 in all BC cell lines, enhancing NK cell-mediated apoptosis and promoting NK cell-tumor cell conjugate formation." (PMID 41102150, 2025). "Exosomal CMTM4 engages macrophages via ICAM1, enhancing cancer cell–macrophage interactions, facilitating p65 nuclear translocation, and promoting M2 polarization, thereby driving tumor progression." (PMID 40433989, 2025). "Similar phenomena were observed in glioblastoma where exposure to IL-1β induced the expression of VCAM-1 and ICAM-1 on tumor cells." (PMID 40071851, 2025). "The biodistribution profile of ICAM‐1–Cy5.5 was further evaluated across five major organs and tumor sites." (PMID 39996528, 2025). "Our previous work identified VCAM1 was 1 of the top 2 enriched genes (along with ICAM1 and the stemness signature) in the lung metastases of PDXs compared with primary tumor cells." (PMID 40955669, 2025). "ICAM1 plays a key role in tumor cell adhesion to LSECs and aids their transmigration across endothelium." (PMID 39875968, 2025). "Adhesion molecules: CAFs can interact directly with tumor cells via adhesion molecules such as N-cadherin, ICAM-1, VCAM-1, etc. and send inhibitory signals to TILs, dampening their cytotoxic responses." (PMID 40805183, 2025). "In Responder specimens, the number of ICAM‐1‐positive tumor cells decreased dose‐dependently with both lidocaine and ropivacaine (mean ± SD for lidocaine 1 μm: 62 ± 37% of control, 10 μm: 35 ± 26%; ropivacaine 1 μm: 75 ± 61%, 10 μm: 59 ± 38%, Figure 8Ai)." (PMID 41028965, 2025). "IHC staining was performed to detect the expression of USP35, STING, HIF-1α, and ICAM1 in the tumor tissues, and the results were consistent with those obtained in vitro." (PMID 41372134, 2025). "The approach preserves adhesion molecules intrinsic to tumor-cell membranes, such as ICAM-1 and EpCAM, thereby enabling selective recognition and binding to homologous tumor cells." (PMID 41209565, 2025). "Upregulation of E-cadherin and TGF-β, and downregulation of N-cadherin and ICAM-1, inhibit tumor growth by suppressing EMT and reduce the invasiveness and metastatic potential of PTC by activating the MAPK, PI3K/AKT, and p16/Rb pathways." (PMID 40230479, 2025). "Clinical application faces challenges due to ICAM-1's expression on normal endothelial and immune cells, raising concerns about off-tumor effects." (PMID 40597436, 2025). "The results of the cytotoxicity experiments strongly support the evaluation of the tumor growth inhibition rate of ICAM‐1–Dxd in TNBC model mice." (PMID 39996528, 2025). "IL-6 also appears to be essential for the upregulation of E-selectin, P-selectin, L-selectin, and ICAM-1, as shown by IL-6 antibody-mediated blockade in multiple tumor models." (PMID 41375025, 2025). "We evaluated the targeting specificity and biodistribution of ICAM‐1‐directed ADCs in 4T1 tumor‐bearing model mice." (PMID 39996528, 2025). "Activated eosinophils up-regulate adhesion molecules (i.e., CD11a, CD11b, ICAM-1) and Siglec-F to enhance their survival and adhesion to tumor cells, thereby leading to contact-dependent degranulation and tumor killing." (PMID 40050933, 2025). "PAK1KD suppressed tumour growth and angiogenesis, promoted vascular normalisation, reduced hypoxia, and increased stromal ICAM-1." (PMID 41294859, 2025).